RN7SL301P (RNA, 7SL, cytoplasmic 301, pseudogene)
Gene: Miscellaneous RNA gene on chromosome 17 (36,110,150 to 36,110,447, forward strand). Ensembl gene ENSG00000276014.
Homologues: Orthologues: chimpanzee Metazoa_SRP (99% identical), macaque Metazoa_SRP (70% identical). Paralogues in human: RN7SL1 (85% identical), RN7SL2 (84% identical), RN7SL3 (84% identical), RN7SL126P (83% identical), RN7SL664P (83% identical), RN7SL218P (82% identical), RN7SL493P (82% identical), RN7SL88P (82% identical), RN7SL448P (82% identical), RN7SL498P (82% identical), RN7SL302P (81% identical), RN7SL660P (81% identical), and 700 more.